EPHB4 (EPH receptor B4)
Diseases named in the same sentence as EPHB4 in open-access papers (continued):
Sharing a sentence is not in itself a finding about the gene and the disease.
tumor (continued). "All cancer cell lines examined showed high levels of EphB4 expression, whereas benign tumour cell lines showed significantly lower levels of EphB4." (PMID 17353927, 2007). "Overexpressed EphB4 provides survival advantage to tumour cells by inhibiting cell membrane originating (extrinsic) apoptosis, and affords an invasive phenotype by promoting tumour cell invasion." (PMID 17353927, 2007). "Although there is limited data on the protein levels of EphB4 in cancers, only recently, data on the biological significance of this protein in tumour biology is being accrued." (PMID 17353927, 2007). "Evidence for a potential role as a tumour promoter comes from EphB4/neuT transgenic mice, which develop tumours more rapidly than neuT transgenic mice." (PMID 17353927, 2007). "EphB4 knockdown inhibits murine tumour xenografts by inducing tumour cell apoptosis and reducing tumour microvasculature." (PMID 17353927, 2007). "Our studies in vitro confirm that EphB4 knockdown leads to a profound inhibition in the ability of tumour cells to migrate and re-populate a wound or invade through basement membrane." (PMID 17353927, 2007). "EphB4 knockdown led to a profound reduction in tumour cell survival accompanied by the induction of apoptosis." (PMID 17353927, 2007). "EphB4 knockdown by systemic antisense administration led to an 85% reduction in tumour volume at 6 weeks." (PMID 17353927, 2007). "There also appeared to be trend towards an increasing level of EphB4 protein in the tumours from the well-differentiated to the moderately and poorly differentiated cancers." (PMID 16171530, 2005). "When this CAR recognizes EPHB4-expressing cells, it induces transduced T cells to acquire effector functions such as activation, proliferation, and cytotoxicity, which may in turn be effective in killing EPHB4-positive tumor cells." (PMID 40842575, 2025). "Immunostaining studies show EphB4 expression is localized to the tumor core, while ephrin-B2 is more widely distributed, suggesting that EphB4-ephrin-B2 interactions may help retain tumor cells centrally and limit peripheral invasion." (PMID 41200151, 2025). "For Cycle Flux Intensity, EPHB4 and ERFE emerge as shared predictors across models; EPHB4 (EPH receptor B4) orchestrates vascular development and tissue remodelling; in oncologic contexts, it frequently connects to angiogenesis and microenvironment-driven tumor progression." (PMID 41411367, 2025). "EphB4 showed a significant correlation with tumor recurrence." (PMID 40421081, 2025). "Additionally, our data suggest that, in contrast to EphB4, genetic deletion of ephrinB2 in the vasculature enhances both local and distant tumor control." (PMID 39489818, 2025). "Furthermore, EphB4-driven modulation of the anti-tumor immune response likely synergizes with changes in cancer cell metastatic capacity to promote distant metastasis." (PMID 39489818, 2025). "Furthermore, castration resistant tumor retains dependence on EphB4 as sEphB4-alb induced remission, concurrent with decrease in PI3K signaling and Myc protein levels." (PMID 40044981, 2025). "Since EphB4 activation induces PI3K pathway, it may enhance the amplitude of PI3K signaling downstream in PTEN deficient tumor cells." (PMID 40044981, 2025). "Downregulation of EphA2 or EphB4 using small interfering RNAs (siRNAs) or antisense oligonucleotides has demonstrated significant impact on cancer cell malignancy in culture and has shown efficacy in inhibiting tumor growth in various mouse cancer models." (PMID 38811954, 2024). "Thus, EPHB4 would have suppressive activity by limiting tumor expansion and dissemination of malignant CRC cells." (PMID 38651144, 2024). "Ephrin type-B receptor 4 (EphB4) promotes angiogenesis by interacting with its ligand, ephrin-B2, expressed on endothelial cells, and promoting endothelial cell migration and proliferation, leading to the formation of new blood vessels within the tumor." (PMID 38686048, 2024).
tumor (continued). "Additionally, EphB4 promotes tumor cell invasion by regulating cytoskeletal dynamics and cell motility." (PMID 38686048, 2024). "We find that EphB4 knockdown in cancer cells enhances metastasis in preclinical HNSCC models by augmenting immunosuppressive cells like T regulatory cells (Tregs) within the tumor microenvironment." (PMID 39091728, 2024). "Notably, EPHA2 upregulation is associated with an increased risk for malignancy and a poor clinical prognosis in various cancer types, and EPHB4 expression is widely observed in neoplastic cells, correlating with tumor progression." (PMID 38612645, 2024). "In tumour vessel xenografts, EPHB4 expression switches the vascularization program from sprouting angiogenesis to circumferential vessel growth, and reduces the permeability of the tumour vascular system via the activation of the angiopoietin-1/Tie2 system at the endothelium/pericyte interface." (PMID 38203852, 2024). "In 2005, research identified the overexpression of ephrin-A3, ephrin-A4, EPHB2, EPHB3, and EPHB4 in ependymoma tumor cells, either from frozen or formalin-fixed tumor samples, but the clinical impact remains unclear." (PMID 38612645, 2024). "Our phopho-western blot data support that activating EphB4 while simultaneously avoiding activation of EFNB2 using various therapeutic strategies such as the EFNB2-Fc-His plasmid provides maximal benefit to reducing local tumor growth and distant metastases." (PMID 39091728, 2024). "However, our previous studies were limited to examining the role of EphB4-ephrinB2 signaling in mediating local tumor growth." (PMID 39091728, 2024). "EphB4 has autonomous function in the tumor cell to promote tumor cell proliferation and survival." (PMID 38985143, 2024). "EphB4 has been reported to have tumor-suppressive properties in breast cancer." (PMID 39839790, 2024). "The complementary results acquired with SPECT and NIRF in mice bearing the EphB4-positive PC-3 tumour revealed two times higher uptake by the tumour tissue and tumour-to-blood ratio for the NP-based conjugate 111In-TNYL-RAW-CCPM than for the NP-free 111In-TNYL-RAW conjugate." (PMID 37241862, 2023). "Disparities between tumour-suppressor and tumour-promoter actions are at least partly attributable to differences in ligand-dependent and ligand-independent signalling, as shown for EphA2 and EphB4." (PMID 36830852, 2023). "However, the role of EphB4 in cancer remains controversial as the Eph-ephrin interactions can both promote and inhibit tumor growth." (PMID 37174034, 2023). "As EphB4 signaling on the cancer cells acts as a tumor suppressor and represents a major target, combining available drug candidates that block bi-directional signaling with potent cytotoxic therapies, such as radiation therapy, would be potentially beneficial." (PMID 35725568, 2022). "To test whether stromal EphB4 plays a role as a tumor promoter, we used the genetically engineered mouse model, EphB4fl/flCol1A2-Cre-ERT, with conditional deletion of EphB4 in collagen I-expressing cells such as fibroblasts." (PMID 35725568, 2022). "In other tumor models, however, disruption of EphB4-ephrinB2 signaling caused no significant changes in tumor vasculature but instead demonstrated a strong mitogenic effect and accelerated tumor growth." (PMID 35725568, 2022). "While it is unclear whether the increase in Tregs is related to enhanced vascularity or trans-endothelial migration, we show that genetic depletion of Tregs reverses the accelerated tumor growth observed with EphB4 knockdown on the cancer cell." (PMID 35725568, 2022). "EphB4 was only located in the tumor core, while ephrinB2 was distributed ubiquitously." (PMID 35163601, 2022). "Together, these data suggest that Tregs partly contribute to the non-tumor cell-intrinsic mechanisms underlying the pro-tumor effects of EphB4 loss on tumor cells in vivo." (PMID 35725568, 2022). "EPO enhances tumor growth and progression via activation of EphB4 signaling." (PMID 34953452, 2022).
tumor (continued). "Both EphB4 and ephrinB2 can signal and the complex EphB4-ephrinB2 signaling can manifest into either pro-tumorigenic or anti-tumorigenic effects as reported in other tumor models." (PMID 35725568, 2022). "The mean increase in Tregs was 1.84-fold greater in the EphB4 shRNA tumors compared to the controls and consistent with the notion that Tregs are involved in immune evasion, inhibiting an effective anti-tumor immune response." (PMID 35725568, 2022). "The recombinant human erythropoietin competes with ephrin-B2 for binding to EPHB4, and therefore, the tumor progression might be mediated via EPO-induced phosphorylation of EPHB4 and subsequent activation of downstream signaling, independent of the EPOR." (PMID 35694408, 2022). "In contrast, augmented activation of EphB4 forward signaling promoted tumor progress." (PMID 35163601, 2022). "In addition to tumor tissues, we also subjected Moc2 EphB4 KO and control cell lines to RNA-seq analysis and observed similar changes in the genes involved in the VEGF signaling pathway including VEGFA, DLL1, NRP2." (PMID 35725568, 2022). "Given the observed increase in Tregs with EphB4 knockdown on cancer cells and their established role in immunosuppression, we hypothesized that Tregs are mediating the accelerated tumor growth at least in part." (PMID 35725568, 2022). "EphB4 can promote tumor angiogenesis through Notch signaling." (PMID 35448036, 2022). "Interestingly, EPHB4 synthetic antisense oligodeoxynucleotides significantly inhibited tumor growth in mice-bearing human OC xenografts." (PMID 35328669, 2022). "We also analyzed the effects of EphB4 and ephrinB2 knockdown in an in vitro real-time IncuCyte assay to determine if the differences in growth are due to a direct effect on the tumor cell’s ability to grow or perhaps due to the signaling triggered within the TME." (PMID 35725568, 2022). "Two large studies investigated the expression of EPHB4 through IHC and real-time RT-PCR in CC tissue samples and reported that high EPHB4 expression correlated with adverse clinical disease stage, larger tumor size, LN metastasis, high MVD, and poor patient OS." (PMID 35328669, 2022). "EphB4/ephrin-B2 signaling may occur inefficiently in peripheral tumor sites of low cellularity, where cell–cell contact is rare." (PMID 35448036, 2022). "If so, we reasoned, that forced activation of EphB4 should reduce tumor growth." (PMID 35725568, 2022). "Our findings establish that, following the loss of EphB4 on the cancer cell, targeted deletion of its binding partner, ephrinB2 on vascular endothelial cells alone does not result in any meaningful tumor growth reduction." (PMID 35725568, 2022). "EphB4 has been detailed in that EphB4 includes a potential oncogenic part and is a critical controller of essential physiological and pathophysiological forms, such as tissue designing, amid advancement, angiogenesis, and tumor movement." (PMID 34336153, 2021). "Previously, we determined that EphB4 protein is present in B16F10 tumor cells." (PMID 34102002, 2021). "In addition, EPHB4 expression in venous endothelium was increased in tumor sections compared with benign ones." (PMID 34445116, 2021). "Exploration of the mechanism of EphB4 suggests that we may regulate the tumour microenvironment of OSCC through the HMGB1-mediated NF-κB signalling pathway." (PMID 34539874, 2021). "EphB4 immunoreactivity was detected in the cytoplasm and membrane of the tumor cells." (PMID 34445227, 2021). "Moreover, the tongue-transplanted tumours of nude mice showed that high EPHB4 expression promoted tumour growth and cervical lymph node metastasis." (PMID 34539874, 2021). "EPHB4 expression, that was reported higher in Barrett esophagus, was also recorded elevated in gastroesophageal carcinomas, tumors of higher stage and in malignant cells at the tumor invasion front." (PMID 34445116, 2021).
tumor (continued). "We performed proof-of-concept in vivo experiments using orthotopic PDAC xenografts in mice and showed that neutralization EphB4-ephrinB2 interaction inhibited tumor growth and metastasis, suggesting that EphB4 is a relevant and druggable therapeutic target for this disease." (PMID 34298619, 2021). "EPHB4-CAR-T cells displayed strong sustained killing activity against Rh30 tumor cells and continuous proliferation even following multiple tumor rechallenge, which indicated that antitumor efficacy was not reduced due to immune evasion, a condition often observed in virally engineered CAR-T cells." (PMID 33816783, 2021). "EPHB4 was expressed in several tumor cell lines including RMS at various levels." (PMID 33816783, 2021). "Indeed, analysis of Apcmin/+ epithelium on the EphB4-deficient background revealed that regulation of cell proliferation, extracellular matrix remodeling, and invasive potential are important mechanisms of tumor suppression by EphB4." (PMID 34244422, 2021). "However, the vast majority of the expression was located at the membrane of malignant epithelial cells, generally throughout the whole tumor section, qualifying EphB4 as an appropriate protein for targeting." (PMID 32751634, 2020). "However, the role of EphB4 in tumorigenesis is way more complicated than in normal tissue, with tumor suppressing as well as tumor promoting effects." (PMID 32751634, 2020). "Moreover, our data suggest that genomic/genetic alterations can promote NB tumour progression by the activation of the druggable gene EPHB4." (PMID 32336043, 2020). "The EphB4 suppression also reduced tumor cells invasion which can be due to MMP9 down regulation." (PMID 32795296, 2020). "In this study, we speculate that EphB4 is the target of PDCD10 in GBM cells and that interfering EphB4 signaling could rescue the phenotype of PDCD10-deficient GBM cells and suppress tumor growth in a mouse model of GBM." (PMID 32850441, 2020). "Due to EPHB4 involvement in tumour angiogenesis, growth and metastasis, we speculated on its potential regulation of cellular proliferation, cell migration and anchorage‐independent growth in vitro." (PMID 32336043, 2020). "While there are some studies in the literature reporting a correlation between tumor stage and expression of EphB4, we observed no such association; in our relatively large cohort EphB4 staining did not vary significantly between different tumor stages." (PMID 32751634, 2020). "Trans-interaction between EphB4 and its membrane-bound ligand ephrin B2 (EFNB2) mediates bi-directional signaling: forward EFNB2-to-EphB4 signaling suppresses tumor cell proliferation, while reverse EphB4-to-EFNB2 signaling stimulates the invasive and angiogenic properties of endothelial cells." (PMID 31949258, 2020). "Functional studies showed that BIDEN-AP could simultaneously activate EphB4-initiated Abl/Crk1 tumor-suppressive signaling in tumor cells and inhibit EFNB2-regulated angiogenic signaling in endothelial cells." (PMID 31949258, 2020). "Many other EPHB4 variants have been identified in other types of tumours and cell lines and catalogued in “The Cancer Genome Atlas project.”24 However, EPHB4 mutations were not described until now in NB." (PMID 32336043, 2020). "Overexpressed EphB4 conduce to tumor development and is regarded as a potential anticancer target." (PMID 32801343, 2020). "The receptor tyrosine kinase EphB4 and its preferred membrane-bound ligand ephrinB2 play a crucial role in both physiological angiogenesis and lymphangiogenesis during embryonic development as well as in pathophysiological processes such as tumor angiogenesis." (PMID 33153234, 2020). "This may be of particular interest, since overexpression of EphB4 has been reported for several tumor entities comprising colon, breast, bladder, endometrium, and ovarian carcinomas." (PMID 29462967, 2018).
tumor (continued). "Moreover, activation of EphrinB2 reverse signaling on adjacent cells, eg endothelial cells, is also important for tumor suppressive effects of EphB4." (PMID 29462967, 2018). "Moreover, there are a number of reports demonstrating the importance of EphB4 and EphrinB2 for postnatal angiogenesis, in particular for tumor angiogenesis and its effect on tumor growth." (PMID 29462967, 2018). "As a consequence of reduced tumor perfusion, a novel and maybe appropriate radiotracer might be under-valuated due to inaccessibility of the target EphB4 for the PET tracer." (PMID 29462967, 2018). "However, inhibition of EphB4 forward signaling using soluble EphB4 resulted in slight decreases in murine aRMS tumor growth." (PMID 28817624, 2017). "Therefore, further research is needed to uncover the mechanisms underlying EphB4 downregulation and its involvement in HCC tumor cell apoptosis." (PMID 29207612, 2017). "A total of 168 tumor/normal pairs were suitable for evaluation of both EphA2 and EphB4." (PMID 28165374, 2017). "Whether a protein target like EphA2 or EphB4 is suitable for image-guided oncologic surgery (IGOS) is determined by its expression pattern in the tumor in comparison with the surrounding normal tissue." (PMID 28165374, 2017). "Overexpression of EphB4 has also been observed in numerous tumor types." (PMID 28942682, 2017). "More information is needed to determine if combination therapies, in conjunction with EphB4 inhibition, could enhance the mild effects of EphB4/EphrinB2 inhibition in aRMS tumor progression." (PMID 28817624, 2017). "However, inhibition of EphB4/EphrinB2 forward signaling with sEphB4-MSA resulted in a decrease in U48484 tumor growth (p = 0.043), suggesting that EphB4/EphrinB2 forward signaling contributes to aRMS progression in vivo." (PMID 28817624, 2017). "For example, ephrinB2 and EphB4 knockouts show defects in arterio-venous patterning and the use of soluble recombinant ephrinB2 or EphB4 proteins can affect migration, adhesion and proliferation of cultured ECs and tumor angiogenesis." (PMID 27467069, 2016). "EPHB4 has tumor suppressor activities in intestinal tumorigenesis." (PMID 27314328, 2016). "Therefore, the dual function of EPHB4 as tumour promoter and suppressor is controlled by the absence and presence of EFNB2 in cancer cells." (PMID 28035996, 2016). "Collectively, our data suggest that ephrinB2 loss promotes tumour invasion by increasing the intrinsic invasive capacity and by permitting the invasion into the EphB2/EphB4 expressing parenchyma through avoiding repulsive interactions, thereby reducing tumour compartmentalization." (PMID 27470974, 2016). "The average durations of DFS and OS in patients with high level circulating CK7, ELF3, EGFR, and EphB4 mRNAs (tumor PBMCs vs. positive control: >2-fold) were significantly shorter than those of patients with normal or downregulation of the four mRNAs in the PBMCs." (PMID 27827952, 2016). "Addition of soluble clustered ligand abrogated these effects supporting a hypothesis that over-expression of EphB4 activates ligand-independent tumour promotion pathways and that ephrin-B2 ligand stimulation is tumour suppressive." (PMID 25831049, 2015). "Furthermore, in vivo experiments targeting xenograft tumour cells expressing EphB4 using anti-sense oligonucleotides and monoclonal antibodies have demonstrated significant inhibition of tumour growth." (PMID 25831049, 2015). "It is possible that “leaky” tyrosine kinase inhibitors may also interact with EphB4, blocking the tumour suppressive signaling pathways and this may contribute to resistance seen in tumours that co-express EphB4 with the intended target receptor." (PMID 25831049, 2015). "EphB4 is a member of the largest family of receptor tyrosine kinases and is an important regulator of fundamental physiological and pathophysiological processes such as tissue patterning during development, angiogenesis and tumour progression." (PMID 25831049, 2015).